MMP2 (matrix metallopeptidase 2)
Diseases named in the same sentence as MMP2 in open-access papers (continued):
Sharing a sentence is not in itself a finding about the gene and the disease.
tumor (continued). "Similarly, the MMP2 showed improved codelivery of siRNA and paclitaxel to tumor cells in vivo (14.4%, sensitive versus 6% uptake, insensitive)." (PMID 29218233, 2017). "In addition, MMP-2 activity is augmented in GBM tumours compared to normal brain and its expression levels is associated with malignant progression." (PMID 28287096, 2017). "Unlike the vast majority of NPs that target the tumor cells or their stroma, the uptake of these enzyme-sensitive NPs in tumor cells is greatly enhanced by metalloproteinase-2 (MMP2), an enzyme secreted at high levels of many tumors, but found in low levels in most normal tissues." (PMID 29218233, 2017). "One of the key MMPs is MMP-2, which is highly expressed in tumor tissue." (PMID 29100297, 2017). "Specifically, MMP-2 may act directly by degrading ECM components like type III collagen or indirectly by activating pro-MMP-2 or by inducing tumor angiogenesis through vascular endothelial growth factors." (PMID 29147947, 2017). "Summarized, these findings substantiate that MMP-2 contributes to tumor aggressiveness." (PMID 28234925, 2017). "Consist with the results obtained from the in vitro study, immune-histochemical analyses demonstrated that the expression levels of EZH2, H3K27me3, MMP2, Vimentin, N-cadherin, ki-67 and Cyclin D1 were downregulated in tumor specimens from the GSK343-treated group." (PMID 29228694, 2017). "As demonstrated by real-time-PCR, U94 expression also induced a strong down-modulation of TWIST, a well-established transcription factor inducing EMT and promoting tumor invasion and metastasis, as well as a concomitant down-regulation of the mesenchymal markers N-cadherin, Snail1, and MMP2." (PMID 28562350, 2017). "Furthermore, systemic treatment of SIS3 also significantly altered the tumour-friendly microenvironment, including suppression on angiogenesis (VEGF expression and CD31+ vessels) and tumour-invasive factors (MMP-2, MMP-9, MMP-13 and CXCR4)." (PMID 28262747, 2017). "The PEG/PCL attached through MMP-2 sensitive peptide bridge shown enhanced intracellular intake of micellar-plex due to exposure of cationic peptide polyarginine (r9) after removal of PEG shell in the tumor microenvironment." (PMID 28785557, 2017). "High levels of MMP-2 also correlate with tumor aggressiveness in various types of cancers." (PMID 28337194, 2017). "We therefore investigated the relation between MMP-2 and tumor subtype using the TCGA dataset." (PMID 28234925, 2017). "MMP-2 instead directly modulates tumor invasion, favoring the spreading of myeloma cells." (PMID 28099912, 2017). "Matrix metalloproteinase 2 (MMP-2), a main member of MMPs, by its ability to degrade the basement membrane type IV collagen, is thought to play a role in stromal and vascular invasion by tumor cells." (PMID 26729052, 2017). "Little is known about Rap1GAP and MMP2 in GC, and here we addressed a significant correlation between Rap1GAP and MMP2, simultaneously, our results showed that overexpression of Rap1GAP suppressed the expression of MMP2 and the migration and invasion capacity of tumor cells." (PMID 28009991, 2017). "In all tumor grades, especially in GBMs, blood vessels were largely MMP-2 positive." (PMID 28234925, 2017). "The decrease of Fas levels found in our study might also suggest a reduction in migration and invasion of tumor cells and the granulocytes population, in addition to the reduced levels of MMP-2 and -9." (PMID 28609459, 2017). "HIF-1α upregulates the levels of cathepsin D (CTSD), urokinase-type plasminogen-activator receptor (uPAR), and matrix metalloproteinase-2 (MMP2) enzymes, implicated in the basement membrane disruption leading intravasation and dissemination of circulating tumor cells (CTCs) in the organism." (PMID 28781970, 2017). "Moreover, these compounds inhibited tumor cell capacity to use MMP2 to degrade ECM by disrupting the integrin-MMP2 protein interaction." (PMID 28678151, 2017).
tumor (continued). "We also observed that MMP-2 and TIMP-3 were downregulated after the knockdown of PANDAR, and MMP-2 and TIMP-3 have been implicated in the regulation of the metabolism of the extracellular matrix, tumor progression and metastasis." (PMID 28545465, 2017). "Western blot was used to demonstrate the expression of ERβ and MMP-2 in mouse tumor tissue." (PMID 28915603, 2017). "In addition, miR-874 is involved in tumor progression by suppressing the protein levels of MMP-2 and uPA and targeting E2F3, HDAC1, AQP3 STAT3 and HCA587/MAGE-C2 in a variety of cancers." (PMID 28525377, 2017). "However, either EGF-enhanced tumor cell invasion or EGF-induced transcription of MMP2 and Twist was compromised by MIIP depletion." (PMID 29038521, 2017). "In addition, MMPs has been reported to play crucial roles in invasion and metastasis of tumor cells, thus protein levels of two of most important MMPs, MMP-2 and MMP-9, in LL/2-R and LL/2-P cells and tumors were measured by western blotting assay." (PMID 28978115, 2017). "MMP-2 is a protease involved in the degradation of ECM in tumor metastasis." (PMID 29285298, 2017). "In addition, the STAT3 signalling pathway regulates tumour invasion and metastasis by regulating MMP2 expression." (PMID 28423603, 2017). "The activity of MMP-2 is considered as an index of tumor invasion ability." (PMID 28915588, 2017). "This suggests that MMP-2 contributes to tumor aggressiveness in astrocytic brain tumors and may have a prognostic potential in patients with GBM." (PMID 28234925, 2017). "In addition, several studies have reported that the secretion or expression of MMPs by tumor cells (including the secreted MMP-2, MMP-9 and the membrane type MMP-14) can lead to the shedding of MICA/B at their surface." (PMID 28423623, 2017). "MMP2, uPA were identified as indicator of tumor invasion and metastasis." (PMID 28388580, 2017). "Similarly, we found that the levels of MMP-2 were significantly reduced in NDV-D90-treated tumor, compared to control, by ELISA and by immunohistochemistry." (PMID 28388537, 2017). "Ursolic acids could inhibit the migration and invasion of tumor stem cells through downregulating MMP-2 and upregulating TIMP-2, while EGCG could inhibit STAT3 signaling pathway." (PMID 28969057, 2017). "Thus, elevated HIF-1α induces the elevation of multiple target genes, e.g. VEGF, CA9 and MMP2, eventually resulting in aberrant proliferation, invasion and tumor progression." (PMID 29100347, 2017). "Given that MMP-2 is systemically expressed, we used novel “bone-seeking” bisphosphonate based MMP-2 specific inhibitors (BMMPIs) to target the skeletal tissue thereby circumventing potential off-target effects of MMP-2 inhibition outside the bone marrow-tumor microenvironment." (PMID 28611279, 2017). "In addition, the suppressive effect of SIS3 on cancer progression was also associated with inhibition of angiogenesis (CD31 and VEGF) and tumour-invasive and metastatic activities, including the expression of MMP-2, MMP-9, MMP-13 and CXCR4." (PMID 28262747, 2017). "Since CTX specifically binds to tumor cells overexpressing MMP-2, the I131-TM-601 may be used as a radioimaging agent while concurrently relaying a tumor-specific, cumulative radiocytotoxic dose of I131." (PMID 30873475, 2017). "Furthermore, previous reports indicated that MMP-9 triggers angiogenesis/ invasion while MMP-2 plays vital role in tumor growth." (PMID 28606135, 2017). "The average MMP-2 expression increased with WHO tumor grade." (PMID 28234925, 2017). "By degradation of the extracellular matrix, a high activity level of MMP2 in GBM may support both tumor invasion and growth." (PMID 29113349, 2017). "Furthermore, to verify the mechanisms of tumor inhibition by Bin1 in vivo, we detected the expression alterations of MMP-2, E-cadherin and BCL-2 in tumor-bearing mice using IHC." (PMID 28152502, 2017).
tumor (continued). "The TLR9-mediated activation of the NF-κB signalling pathway and the associated enhanced expression of matrix metalloproteinase-2 (MMP-2), MMP-7 and cyclo-oxygenase 2 mRNA, all factors associated with tumour progression and migration, can explain the role of TLR9 in cancer." (PMID 29225688, 2017). "The modulation of MMP-2 effectively affects tumor metastasis." (PMID 29100297, 2017). "In other words, MMP‐2 may play a catalytic role in the formation of VM, which is a fast and efficient response mechanism to provide blood to the tumour and provides the major blood supply in the early stage." (PMID 28766880, 2017). "It is possible that a lack of increase of MMP2 expression in canine tumour stroma is due to lack of isolation of tumour associated macrophages in our case, as we sought to avoid areas of obvious inflammation when isolating stroma." (PMID 28531107, 2017). "The MMP2 and MMP9 promoter region contains cis-regulatory elements, including one NF-κB binding site, and NF-κB binding to this site is reportedly closely associated with tumor cell invasion." (PMID 27556184, 2016). "Interestingly, U87 MMP2-KD tumors with reduced MMP2 activity also had a slower tumor growth rate compared to control tumors." (PMID 26923459, 2016). "Integrins, particularly αvβ3, are involved in angiogenesis through interaction with vascular epithelial growth factor (VEGF) receptor, fibroblast growth factor 2 (FGF2), platelet-derived growth factor (PDGF), and matrix metalloproteinase-2 (MMP-2) which collectively aid tumor development and growth." (PMID 27556860, 2016). "In addition, fibroblast- or tumor cell-conditioned media upregulated the secretion of MMP-2 and MMP-9 in HNSCC cells." (PMID 26851944, 2016). "Therefore, the study provides novel evidence that ANG plays an important role in the promoter activation of the tumor oncogenic gene MMP2, which likely contributes to ANG oncogenic activity." (PMID 27317771, 2016). "Taken together, our present findings implicate that the blockade of MMP2 and CD44 expressions as well as MMP-2 activity may contribute to the inhibitory effect of grifolin on tumor cell migration and adhesion." (PMID 27626695, 2016). "Some other studies also revealed that up-regulation of MMP-9 expression enhanced the chemotherapeutic resistance, and SSTR2 could suppress tumor growth and metastasis by inhibition of MMP-2 and -9 expressions indirectly." (PMID 27825139, 2016). "Similarly, we identified CCL2/CCR2 axis as a tumor promoter in NPC metastasis through upregulating MMP2/9 via ERK1/2 pathways." (PMID 26701209, 2016). "The EPQ mixture without quercetin (NM) also has shown potent anticancer activity in vivo and in vitro in a few dozen cancer cell lines by inhibiting tumor growth and metastasis, MMP-2 and -9 secretion, invasion, angiogenesis, and cell growth as well as induction of apoptosis." (PMID 27618095, 2016). "This may suggest that MMP-2 protein is secreted from tumor cells to the stroma where it modifies the immune response cells." (PMID 27429508, 2016). "aMMP2-SIP imaging was performed in multiple tumor models with varying MMP2 expression and activity." (PMID 26923459, 2016). "At 25 days after injection of HepG2 cells that were transfected with siRNA-TM4SF1, tumor expression of MMP-2, MMP-9, and VEGF were significantly lower, but tumor expression of caspase-3, caspase-9, and TIMP were higher, relative to injection with control cells (p < 0.01 for all comparisons)." (PMID 27153056, 2016). "For example, MMP-2 protein expression is significantly associated with histological grade, TNM stage, tumor size, and LNM in RCC, suggesting that MMP-2 may serve as a biological marker for the prognosis in RCC." (PMID 27807511, 2016). "Thus, embelin appears to inhibit angiogenesis and MMP2 expression, and thereby limiting tumor progression." (PMID 26799669, 2016).
tumor (continued). "Interestingly, in the cell lines in vitro and tumor nodules from nude mice in vivo, downregulating Anxa3 expression significantly decreased MMP-2 and N-cadherin expression and increased E-cadherin expression." (PMID 27995049, 2016). "In particular this would allow to determine the origin of MMP2 from tumor or stromal tissue." (PMID 26243272, 2016). "In addition, calpain-4 overexpression can activate FAK (Focal adhesion kinase)-Src signaling pathways and up-regulate MMP2 expression to induce tumor metastasis." (PMID 27689993, 2016). "Also, overexpression of Aurora-A promotes ESCC development by enhancing invasion as well as MMP-2 expression in tumor cells, which can occur by activating p38-MAPK and Akt signalings." (PMID 27793005, 2016). "The mechanism of radiation-induced knockdown of LGMN suppressing cell migration and invasion was next investigated with a focus on MMP9 and MMP2, a kind of gelatinase has the unique ability to degrade extracellular matrix components and facilitate tumor migration and invasion." (PMID 27656894, 2016). "In addition, MMP2/9 protein levels were reduced in tumor tissue using Immunohistochemistry analysis (*P < 0.05, ****P < 0.0001, vs control)." (PMID 26811493, 2016). "In addition, the detachment of the PEG chain by the high levels of MMP2 in the tumor environment, expose the previously-hidden PEI to cells for better internalization of both siRNA and PXL." (PMID 28335259, 2016). "Reports also indicate the up-regulation of MMP2, MMP3, and/or MMP9 to be associated with tumor aggressiveness, suggesting that SIBLING-MMP complexes may facilitate tumor cell metastasis." (PMID 27331624, 2016). "MMP2/9, β-catenin and ezrin drives tumor progression and metastasis of cancer." (PMID 26943769, 2016). "MMP2 plays important functions in tumour proliferation and metastasis." (PMID 27447567, 2016). "Thus, downregulating MMP-2/9 expression or decreasing enzymatic activities in the tumour microenvironment is crucial in inhibiting angiogenesis, tumour invasion and metastasis." (PMID 27188337, 2016). "A MMP2 specific probe was developed to distinguish cancer foci (delineating the primary tumor in malignant glioma, medulloblastoma, prostate and intestinal cancer, sarcoma, as well as metastatic cancer foci) from adjacent normal tissues: the chlorotoxin:Cy5.5 (CTX:Cy5.5)." (PMID 27145373, 2016). "However if MMP2 activity is detected specifically, it can be beneficial to monitor tumor progression and tumor responses to treatment." (PMID 26923459, 2016). "Δ9-THC also reduced tumor growth and the expression of MMP-2 in tumors of Δ9-THC-treated patients." (PMID 27774065, 2016). "Similarly, embelin treated tumor exhibited decreased expression of MMP2 in stromal cells based on immunostaining." (PMID 26799669, 2016). "Notably, several lines of evidence show a positive correlation between MMP-2 and -9 expression and tumour progression and metastasis in various human cancers." (PMID 27589705, 2016). "MMP-2 is up-regulated following different irradiation protocols in various tumor types such as glioblastoma, pancreatic, lung and colorectal cancers, leading to increased tumor invasion." (PMID 27064581, 2016). "However, MMP knock-out mice revealed MMP9 as a key regulator of angiogenesis in this system, while MMP2 rather contributed to tumor growth." (PMID 26979530, 2016). "Additionally, we show that miR-204 acts as a tumor suppressor by regulating Rab40b and Tks5 expression and consequently inhibiting MMP2 and MMP9 targeting, which leads to a decrease in invadopodia-associated ECM degradation." (PMID 27789576, 2016). "Furthermore, Anxa3 knockdown significantly decreased MMP-2 and N-cadherin expression and increased E-cadherin expression both in cell lines in vitro and in tumor nodules examined during in vivo tumorigenesis assays." (PMID 27995049, 2016).
tumor (continued). "Our preliminary data demonstrate that the ratio of MMP2/MMP9 activity might be a valuable prognostic marker for the response to chemotherapy that can easily be analyzed by zymography in tumor tissue samples." (PMID 26979530, 2016). "For patients with ER negative tumours, the MMP-2 TT genotype was associated with poor survival (2/8 patients alive at end of study, 25%) compared to the CC or CT genotypes (59/70, 84%; p < 0.001)." (PMID 27051552, 2016). "Our acquired data manifested that RES could inhibit gelatinolytic activity and suppress the expression of MMP-2 in GICs and that MMP-2 was a RES-responsive mediator, which leads to the degradation of ECM, causing subsequent tumor invasion and migration." (PMID 26043036, 2015). "Based on our current findings, we suggest CEBPD amplification/overexpression in tumor samples can be a surrogate biomarker to positively select patients that might benefit from MMP2 targeted therapy." (PMID 26307680, 2015). "All the results suggested Angio-DOX-DGL-GNP could accomplish large-to-small shrinkage in response to MMP-2, thereby penetrating into the core area in tumor sites." (PMID 26517810, 2015). "Moreover, we reported that SCRN1 promotes colon cell proliferation and enhances the secretion of MMP-2/9 to accelerate cancer cell invasion and tumor metastasis." (PMID 25814779, 2015). "One of the MMPs of particular significance in tumor contexts is MMP2." (PMID 25557170, 2015). "In agreement with our data showing increased invasiveness of 12 T cells compared to controls, increase in the matrix metalloproteases (MMP2/3/9) involved in extracellular matrix reorganization of the tumor microenvironment during EMT were found to be upregulated in 12 T cells." (PMID 26597727, 2015). "However the expression of MMP-2 was downregulated in the tumor tissues of the nude mice in the pEGFP-C1-CDX2 group." (PMID 26005051, 2015). "In addition, MMP-2 protein levels have been shown to increase in all tumor-derived fibroblast lines." (PMID 25855056, 2015). "Ten articles contained information of the impact of MMP-2 expression on tumor sizes, nine on lymph nodes status, two on distant metastasis, eight on TNM stage, nine on histological grade, ten on estrogen receptor status and nine on progesterone receptor status." (PMID 25816052, 2015). "A possible reconciliation for these observations is that cross-activation between the Ras-MAPK and PI3K-mTORC1 pathways might co-regulate MMP-2 expression to promote tumour invasiveness." (PMID 26597054, 2015). "Bioinformatics analysis combined with tumor metastasis PCR array showed that matrix metalloproteinase 2 (MMP2) and PTEN could be important target genes of miR-29b." (PMID 26063204, 2015). "The expression of MT1-MMP and MMP-14 is elevated in tumours of the colon and has been described as a target of the Wnt pathway MMP-2 is related to tumour invasion and it has been demonstrated that there is a greater expression of its transcription on the invasive front of the colon tumour." (PMID 25932044, 2015). "In the present study, MMP-2 expression was found in both tumor cells and stromal cells." (PMID 25816052, 2015). "Furthermore, the correlations between miR-652 and E-cadherin (r = 0.9106)/N-cadherin (r = −0.7309)/Vimentin (r = −0.8416)/MMP-2 (r = −0.8971) in primary tumor mass were further identified." (PMID 26498682, 2015). "Moreover, HSP90 also promotes activation of extra‐cellular proteins such as MMP‐2, leading to enhanced tumour invasiveness." (PMID 25241147, 2015). "In addition, miR-33b antagomir attenuated the inhibitory effect of cordycepin on the expressions of MMP-2, MMP-9 and CD44 which are associated with tumor invasiveness at mRNA levels." (PMID 25868853, 2015). "Experiments in vitro validated that SCRN1 may promote cancer cell proliferation and secretion of matrix metalloproteinase-2/9 (MMP-2/9) proteins to accelerate tumor progression." (PMID 25814779, 2015).